PXN (paxillin)
Diseases named in the same sentence as PXN in open-access papers (continued):
Sharing a sentence is not in itself a finding about the gene and the disease.
cancer (continued). "The decreased tumorigenicity of paxillin Y88F mutants described previously indicates this phosphorylation event is important in cancer development." (PMID 27447856, 2017). "The FAK/paxillin pathway regulates small Rho GTPases including RhoA, Rac1, and Cdc42, which are critical determinants of cancer cell migration." (PMID 28214467, 2017). "Contrastingly, proteins that promote cell adhesion such as Paxillin (PXN), breast cancer anti-oestrogen resistance 1 (BCAR1) and Caveolin-1 (Cav-1) were upregulated." (PMID 28217176, 2017). "Coherently, alterations in Paxillin expression levels can affect migratory performance, as shown by different classic reports linking its expression with cancer metastatic potential." (PMID 29127427, 2017). "Disrupting the interaction between FAK and paxillin blocks the migration and invasion of cancer cells." (PMID 28423510, 2017). "Inhibiting FAK/paxillin signaling by a sialyltransferase inhibitor effectively retards cancer cell migration." (PMID 29234409, 2017). "Currently, increasing evidence has demonstrated that the FAK/paxillin signaling pathway participates in the processes of cancer invasion and metastasis via different molecular mechanisms." (PMID 28423510, 2017). "Based on the molecular complexity of the JNK signalling pathways involved in cancer metastasis and development, several metastasis-associated targets were detected in the present study, including the EMT markers, MMP2/9 and Paxillin/FAK." (PMID 29088796, 2017). "This allows the activation of NF-kB and the promotion of paxillin expression, thus stimulating cell invasion, migration, and cancer progression." (PMID 28214467, 2017). "The elucidation of paxillin function regulation is crucial for the development of pharmacologic or clinical strategies aimed to controlling cancer development and metastasis." (PMID 28214467, 2017). "Increased activity of focal adhesion proteins such as focal adhesion kinase (FAK) and paxillin have been correlated with poor patient survival and increased malignancy of blood and other cancers." (PMID 29017562, 2017). "Carcinoma invasiveness is highly associated with activation of integrin and its downstream signaling pathway, including FAK, paxillin, Rho and metalloproteinases (MMPs)." (PMID 28076322, 2017). "It is therefore clear that targeting FAK in cancer therapy is likely to also suppress paxillin-mediated functions." (PMID 26980710, 2016). "Based on these findings, we propose that by binding and inhibiting septins, 3MCIC can deplete paxillin and disrupt stress fibers, and consequently block cancer cell migration and metastasis." (PMID 27525972, 2016). "Extensive research on cancer has documented that Fyn associates with intracellular substrates like FAK, paxillin, and β-adducin to regulate cytoskeletal architecture and cell-cell interactions." (PMID 26881253, 2016). "According to previous reports, FAK has to bind to both LD2 and LD4, failing which phosphorylation during signalling is reduced, which is observed in case of cancer, thus resulting in abnormal functioning of paxillin." (PMID 26928467, 2016). "Paxillin is present in low levels in normal brain tissue and elevated in many cancers with the levels correlating with higher invasive potential and migration." (PMID 26940200, 2016). "In this regard, studies on the inhibitory effects of an ezrin inhibitor, NSC668394, on the ezrin-related signaling such as Src and paxillin and on the migration of cancer cells are underway in our researches." (PMID 25866790, 2015). "JNK signaling has also been shown to regulate cancer cell migration through phosphorylation of paxillin." (PMID 25337707, 2014). "The antimigratory and anti-invasive activities of (-)-oleocanthal were associated with suppression of activation of Brk, paxillin, and Rac1 in response to HGF stimulation in MDA-MB-231 cancer cells." (PMID 24849787, 2014).
cancer (continued). "Overexpression of PXN increases cell migration and/or metastasis in various cancer types including PCa." (PMID 25504435, 2014). "Paxillin expression was higher in the elder carcinoma patients than in the younger carcinoma patients (P<0.05)." (PMID 24348846, 2014). "Paxillin expression was lower in the younger carcinoma patients compared with that in the elder carcinoma patients (P<0.05)." (PMID 24348846, 2014). "Fascin-1, ezrin and paxillin are regulated by microRNAs and take part in the modulation of malignant progression in carcinoma." (PMID 23209815, 2012). "Lastly, Paxillin phosphorylation at S83 was detected, a site previously linked to Rac1 activation and cytoskeletal remodeling via ERK signaling, processes already observed in our experiments and that are important for cancer metastases." (PMID 40629272, 2025). "In addition, paxillin is an essential player in pathological conditions, including oxidative stress, inflammation, endothelial cell barrier dysfunction, and cancer development and metastasis." (PMID 40004187, 2025). "Therefore, disrupting the FAT-paxillin protein–protein interaction (PPI) is a desirable strategy to inhibit the FAK pathway in cancer." (PMID 40021642, 2025). "This approach could be particularly effective in cancers where paxillin or kindlin is overexpressed, reducing their abundance rather than merely inhibiting their function." (PMID 40001476, 2025). "PXN (Paxillin) is involved in focal adhesion and cytoskeletal reorganization, and is associated with enhanced motility and epithelial – mesenchymal transition (EMT) in cancers." (PMID 40964608, 2025). "Research on how paxillin and kindlin influence cell adhesion, migration, and signal transduction has identified these proteins as potential therapeutic targets, particularly for cancer treatment." (PMID 40001476, 2025). "Paxillin is involved in cytoskeletal reorganization and the formation of focal adhesions, exerting a crucial role in the migratory and metastatic processes of cancer cells." (PMID 40821990, 2025). "Notably, in numerous cancers, PXN is overexpressed relative to FAK, which would suggest a PXN/FAT structural model similar to that described here." (PMID 40532016, 2025). "Furthermore, it was discovered that there is a strong link between paxillin levels and cancer progression and spread." (PMID 39048985, 2024). "Aberrant activation of the FAK signaling pathway (FAK/paxillin/p130cas axis) is known to drive cancer progression and metastasis, which may promote cell motility by altering the dynamics of the actin cytoskeleton." (PMID 39654023, 2024). "Notably, this reduction is achieved through the inhibition of the FAK/paxillin/Akt signaling pathway, which plays a crucial role in cancer development." (PMID 38791186, 2024). "In addition, the abnormal expression of paxillin in cancer patients is also closely related to the poor clinical prognosis of the patients." (PMID 37175948, 2023). "Overexpression of Paxillin has been reported in a number of different human cancer types." (PMID 36723624, 2023). "In addition, paxillin can directly interact with the pro-survival proto-oncogene Bcl-2 to promote cancer cell survival." (PMID 37175948, 2023). "Moreover, to some important extent, the abnormal expression of paxillin has an effect on the survival of cancer cells." (PMID 37175948, 2023). "However, the special structure and function of paxillin make it play an indispensable role in the development of cancer." (PMID 37175948, 2023). "In addition, we detected an increased number of p-paxillin-positive spots in the cytoskeleton of cancer cells in the MF toward DRGs compared with the back front (BF) that faces the empty ECM gel." (PMID 37607005, 2023). "While the roles of Fyn and paxillin in cancer cell migration have been reported, the exact mechanism through which Fyn influences paxillin function remains unclear." (PMID 37958964, 2023).
cancer (continued). "Furthermore, we identified a strong reduction of paxillin phosphorylation in cancer cells of recipients treated with 6B345TTQ (4.72% of total area) compared with control mice treated with DMSO (9.79% of total area)." (PMID 37607005, 2023). "Therefore, future research needs to fully combine paxillin with other prognostic factors to explore the relationship with poor clinical prognosis and to improve the sensitivity and specificity of paxillin in cancer prognosis." (PMID 37175948, 2023). "Therefore, paxillin is considered to have potential specific effects in different cell lines or cancer types." (PMID 37175948, 2023). "Indeed, treatment of both patient-derived cancer cell lines with rCCL2 significantly enhanced the phosphorylation of paxillin already after 15 minutes of treatment, as well as of its downstream mediators Src and Erk." (PMID 37607005, 2023). "Additionally, cancer cells can also use the integrin/paxillin control mechanism to release tumor necrosis factor-α (TNFα)-converting enzyme-containing vesicles to improve their own growth microenvironment." (PMID 37175948, 2023). "FAK and paxillin activity are highly regulated in PDAC cancer cell migration and invasion." (PMID 37046830, 2023). "Paxillin and FAK are key components of focal adhesions and changes in their expression or localization and their phosphorylation status are often associated with cancer cell metastasis." (PMID 37175948, 2023). "Many scholars have also recognized that the abnormal expression of paxillin is related to the prognosis, metastases, invasion, survival, angiogenesis, and other aspects of malignant tumors, suggesting that paxillin may be a potential cancer therapeutic target." (PMID 37175948, 2023). "The prognostic value and clinical significance of paxillin in different cancers." (PMID 37175948, 2023). "Likewise, the inhibition of the FAK-paxillin pathway can also inhibit the invasion of other cancer cells." (PMID 37175948, 2023). "Furthermore, the FAK/Paxillin signaling axis also plays an important role in promoting cancer cell migration and invasion." (PMID 36160416, 2022). "Recent studies have shown that paxillin phosphorylation promotes the adhesion between cancer cells and matrix, inhibits the adhesion between cells, and promotes pseudopodia formation of cancer cells, thus promoting invasion and metastasis of cancer cells." (PMID 34268882, 2021). "Therefore, the aim of this study was to investigate the role of SphK1 on autophagy, focal adhesion paxillin, and the metastatic capabilities of cancer cells in vitro and in vivo." (PMID 34268882, 2021). "Importantly, the focal adhesion kinase/PXN pathway plays a crucial role in cancer cell migration by regulating small Rho GTPases." (PMID 34135128, 2021). "Previous study showed paxillin phosphorylation promoted adhesion between cancer cells and matrix, inhibited adhesion between cells, enhanced pseudopodia formation, invasion, and metastasis of cancer cells." (PMID 34268882, 2021). "Importantly, PXN is also an essential player in pathological conditions including cancer development and metastasis." (PMID 35008571, 2021). "This association between PXN and TME might be another reason for the prognostic implications of PXN in various cancers." (PMID 34135128, 2021). "It is an interesting finding that the expression of PXN differs depending on the type of cancer." (PMID 34946859, 2021). "Furthermore, we demonstrated that aberrant expression of PXN facilitated cancer cell migration and invasion." (PMID 34946859, 2021). "Furthermore, the role of SphK1‐driven autophagy activation and its influence on focal adhesion paxillin and the metastatic capabilities of cancer cells were examined." (PMID 34268882, 2021). "Moreover, we found that PXN promoted the activation of the AKT signaling pathways which was involving in the cancer cells anoikis." (PMID 33033511, 2020).
cancer (continued). "Among these target genes, we focused on PXN, which showed the most significant association with RCC patient survival in the multivariate analysis and has been reported previously as an oncogene in other types of cancers." (PMID 33322675, 2020). "Other significantly enriched pathways (FDR q-value < 0.05) were “hypoxia”, “KRAS signaling”, “myogenesis”, “angiogenesis”, and “apical junction”, supporting the hypothesis that PXN is related to the metastatic ability of cancer cells." (PMID 33322675, 2020). "Moreover, there was a positive correlation between SEPT9 and paxillin in the cancer tissues (γ = 0.665, P = 0.000)." (PMID 31558699, 2019). "By disrupting this mechanism, SPTAN1 could have influences on cell detachment, apoptosis, and migration of cancer cells as described for PXN and FAK, both of which are also described to be upregulated in several cancers." (PMID 31186638, 2019). "SGSM2 downregulation enhanced the phosphorylation of focal adhesion kinase (FAK; Y576/577), decreased the expression of epithelial markers such as E-cadherin, β-catenin, and Paxillin, and increased the expression of Snail and Twist-1, which reduced cell adhesion and promoted cancer cell migration." (PMID 30744493, 2019). "Studies indicate that MAPK3, CTTN and PXN regulate chemo or TKIs-based targeted therapy in cancer." (PMID 29556515, 2018). "Paxillin binds to many proteins involved in effecting changes in the organization of the actin cytoskeleton, which is needed for cell motility events including cancer metastasis." (PMID 30462668, 2018). "Recent reports revealed repression of FAK/paxillin/Rac/MMP downstream signaling pathways could effectively inhibit the invasive ability of cancer cells." (PMID 28350337, 2017). "Therefore, FAK/paxillin pathway activation is recognized as a potential predictor of cancer metastasis." (PMID 28423510, 2017). "Next, focal adhesion kinase (FAK)/paxillin/Src is related with cancer cells’ migratory ability." (PMID 28350337, 2017). "A growing number of signaling molecules have been shown to promote or regulate cell migration of cancer cells through the phosphorylation of paxillin at Tyr118 and Ser178 by FAK, which alters the organization of FAs, with the consequent promotion of cell motility." (PMID 28214467, 2017). "Importantly, paxillin is also an essential player in pathological conditions including oxidative stress, inflammation, endothelial cell barrier dysfunction, and cancer development and metastasis." (PMID 28214467, 2017). "Our data revealed that rhodomycin A inhibits FAK, JNK, Paxillin, and p130cas activity and the protein expression in PC9 and PC9/gef cell lines, which may cause the decrease of cancer cell invasion and migration ability." (PMID 26312766, 2015). "Here, we present evidence from cell and animal models to demonstrate that stabilization of Bcl-2 protein by phosphorylation at Serine 87 (pBcl-2-S87) via PXN-mediated ERK activation is responsible for cancer cell invasiveness and occurs via upregulation of MMP2 expression." (PMID 25826088, 2015). "Furthermore, western blot revealed the ouabain-mediated downregulation of p-FAK (Y925), p-paxillin (Y118), p130CAS, and Na+/K+-ATPase subunits that have been shown to be involved in the migration of cancer cells." (PMID 25866790, 2015). "Likewise, a dependence on integrin sialylation has been reported for FAK/paxillin-mediated signaling, and for cancer angiogenesis and metastasis pathways." (PMID 24878505, 2014). "Paxillin may be a potential predictor of metastasis and an independent prognostic factor for recurrence and may target phosphorylation to mitigate the impact of chemotherapy-resistant cells on cancer progression, thereby improving patient outcomes." (PMID 40861820, 2025). "These isoforms of Paxillin may play distinct functions in cell adhesion regulation of cancer cells." (PMID 41462902, 2025).
cancer (continued). "Moreover, the importance of the PXN/FAT interaction in both cancer metastasis and drug resistance mechanisms suggests that it may be a viable therapeutic target despite its flexibility as was recently supported." (PMID 40532016, 2025). "Therefore, a further understanding of paxillin’s function may lead to the development of new cancer therapies developed against paxillin." (PMID 37175948, 2023). "However, increasing evidence suggests that paxillin is aberrantly expressed in many cancers." (PMID 37175948, 2023). "In addition, paxillin can also promote cancer cell migration by regulating the EMT process." (PMID 37175948, 2023). "However, there are far fewer studies investigating Paxillin phosphorylation in cancer progression." (PMID 36723624, 2023). "Therefore, PTEN inactivating mutations, which are commonly found in many types of cancer, may lead to overactivation of the PI3K/AKT/NF-κB pathway, which increases paxillin transcription and subsequently results in the invasive properties of cancer cells." (PMID 37853467, 2023). "Paxillin may be an important regulator of cancer metastasis." (PMID 37175948, 2023). "Thus, the integrin/FAK/paxillin signaling was investigated to determine whether the apigenin-inhibited cancer cell migration inactivated the integrin/FAK/paxillin signaling pathway." (PMID 35406599, 2022). "However, the roles of PXN in human pan-cancer are not well understood." (PMID 34135128, 2021). "The sites of protein phosphorylation on PXN might be potential targets for cancer treatment." (PMID 34135128, 2021). "Therefore, discrepancies of PXN expression in various cancers indicated that PXN may have different biological functions in different types of cancer." (PMID 34135128, 2021). "PXN-mediated pathways may be therapeutic targets for attenuating drug-resistance in cancer cells." (PMID 33322675, 2020). "Therefore, inhibition of either the FAK/paxillin or MAPK pathway in cancer cells could be an effective strategy for preventing cancer cell migration and invasion." (PMID 28423510, 2017). "In cancer cell migration, several reports have indicated that the FAK-Src complex promotes activities of many FAK-associated Src substrates, including p190RhoGAP, paxillin, and p130cas, which play an important role in the reorganisation of the actin cytoskeleton and motility." (PMID 26312766, 2015). "Staining for vinculin and paxillin aligned with the peripheral degradation areas, suggesting that rheumatoid synovial fibroblasts may use both invadopodia and focal adhesions to degrade matrix, similarly to cancer cells." (PMID 25280866, 2014). "Paxillin-mediated signaling may therefore be critical for determining whether a cell migrates along a planar (2D) basement membrane or through a 3D interstitial matrix, as occurs, for example, during epithelial-mesenchymal transitions in cancer metastasis." (PMID 22194823, 2011). "Small-molecule inhibitors disrupting paxillin–FAK interactions and kindlin–integrin binding have shown potential in reducing cancer invasiveness." (PMID 40001476, 2025). "Furthermore, targeting FAK in cancer therapy may also inhibit paxillin-mediated functions." (PMID 37175948, 2023). "Remarkably, though, treatment of both cancer cell lines SU.86.86 and T3M4 with the CCR4 antagonist (C021) decreased paxillin phosphorylation in a time-dependent manner." (PMID 37607005, 2023). "We also show that TGF-α promotes the secretion of CCL2 from DRG neurons, which, in turn, activates the cancer cell cytoskeleton through CCR4, paxillin phosphorylation, and cell protrusion formation." (PMID 37607005, 2023). "Several key structural and regulatory proteins involved in focal adhesion dynamics are dysregulated in cancer to enhance cell invasion and migration, including integrins, FAK, Src kinase, paxillin, and the actin and microtubule cytoskeletons." (PMID 37046830, 2023).